HSF1 (heat shock transcription factor 1)
Diseases named in the same sentence as HSF1 in open-access papers (continued):
Sharing a sentence is not in itself a finding about the gene and the disease.
cancer (continued). "As HSF1 plays a pleiotropic role in cancer, its dysregulated expression in cancer and its relationship with the prognosis of cancer patients imply that HSF1 could be utilized as a biomarker for patient prognosis and a promising molecular target for cancer treatment and chemoprevention." (PMID 35180892, 2022). "In addition, HSF1 was investigated as a biomarker for patient outcomes in various cancers." (PMID 35928554, 2022). "Additionally, HSF1 has been found to be overexpressed or activated in a variety of cancers." (PMID 36010849, 2022). "Additionally, HSF1 has been reported to drive oncogenesis by mediating the activation of genes that enable the initiation and maintenance of cancer cells through shifts in processes such as cell cycle control, metabolism, protein translation, and proliferation." (PMID 35485710, 2022). "Thus, in addition to the fact that HSF1 drives a transcriptional program distinct from heat shock to support malignant phenotype, proteotoxic stress (e.g., induced by therapeutic hyperthermia) can elicit different effects depending on the level of HSF1 and the type of cancer." (PMID 36010586, 2022). "In addition to maintaining mitochondrial proteostasis, HSF1 can also participate in cancer initiation, development and progression by modulating the tumor microenvironment, inhibiting apoptosis, repairing the genome, promoting cell proliferation and migration and reprogramming metabolism." (PMID 35180892, 2022). "Thus, some considered the possibility that HSF1 plays a role in cancer." (PMID 35053319, 2022). "However, most studies on the function of HSF1 in cancers were limited to a specific type of cancer." (PMID 34239690, 2021). "These proteins may provide mechanistic insight into how HSF1 mediates gene repression, a largely unexplored aspect of HSF1 biology that contributes to disease conditions through a network of HSF1-repressed genes in cancer and other gene targets involved in inflammation." (PMID 33208463, 2021). "Hsp synthesis is tightly regulated at the transcriptional level by heat shock factor 1 (HSF1), which is considered the main regulator of the short-term induction of heat stress, and its activation/expression is used as a prognostic marker for a wide variety of cancers including kidney carcinoma." (PMID 34845419, 2021). "Future prospective and experimental studies of the HSF1 expression and immune cell infiltration in different cancer populations may provide additional insights into the tumor mechanisms and the development of therapeutic strategies targeting HSF1 to improve the therapeutic efficacy of immunotherapy." (PMID 34239690, 2021). "HSF1 inhibition by using HSF1 shRNAs or KRIBB11 decreased the expression of HSF1 downstream proteins, such as HSP70 and HSP27, and also decreased the expression of HSP90/HSP70/BAG3 client proteins, such as BCL2, MCL1, EGFR, MET, and AXL, causing apoptosis of EGFR-TKI-resistant cancer cells." (PMID 34203709, 2021). "However, the abnormal activation alone HSF1 is not sufficient to cause cancer initiation, which means that the pro-tumorigenesis effect of HSF1 requires the contributions of other cancer-promoting mechanisms (such as the KRAS oncogene mutation)." (PMID 33422093, 2021). "The cytoprotective response mediated by HSF1 counteracts the cytotoxic effect of proteasome inhibitors, and thus, HSF1 inhibition might be effective to overcome proteasome inhibitor resistance in cancer cells." (PMID 33376136, 2021). "Together, they can prevent the oligomerization and the activation of various client proteins, such as HSF1, IκB, and block caspase activation, thereby promoting immortality of cancer cells and the general resistance to physical stresses and chemotherapeutic agents." (PMID 33937334, 2021).
cancer (continued). "In this regard, it has been recently demonstrated that in colon cancer, stromal HSF1 drives the transcription of genes encoding matrix proteins (FN1, LAMA1), matrix enzymes (MMP7, MMP9), and matrix chaperones (SERPINH1/Hsp47), inducing ECM remodeling and leading to cancer progression." (PMID 34198675, 2021). "Additionally, it has been reported in several carcinomas that HSF1 regulates HSP70." (PMID 34064083, 2021). "Thus, such amino acid replacements in Hsf1 could contribute to increased chaperone levels in cancer cells and thereby to cancer cell fitness and resistance to therapeutic intervention." (PMID 32490574, 2020). "Targeting HSF1 could be a potential strategy for the intervention of β-catenin-driven cancers." (PMID 32838807, 2020). "Therefore, controlling HSF1 and the stress response may ultimately be an important factor in successfully treating some cancers." (PMID 32331382, 2020). "It has been reported that Dkk3 might orchestrate concomitant activation of β-catenin and YAP/TAZ in cancer-associated fibroblasts (CAFs) by interfering with the Kremen negative regulator and increasing cell-surface levels of LRP6 as an HSF1 effector, required to promote tumor aggressiveness." (PMID 33425757, 2020). "The study demonstrated cancer-type-specific inhibition of HSF1 by targeting an upstream oncogene activator, an approach that may apply to other tumor contexts where oncogenic drivers lead to HSF1-mediated increased chaperome expression." (PMID 32331382, 2020). "Since the HSF1 gene is located in 8q24.3, we assessed if HSF1 overexpression in cancer could be linked to genome organization rather than a global change in transcriptional programming." (PMID 31699156, 2019). "Thus, taken together, our findings demonstrate that HSF1 may be a potential target for statin-based treatment and cancer management through a low-cholesterol diet in HCC patients." (PMID 31540279, 2019). "Thus, activation of the HSF1 > TGF-beta and CXCL12 mechanism might be predicted to suppress anti-tumor immunity, and may represent a beneficial feature of targeting HSF1 in cancer." (PMID 31514477, 2019). "In addition, both Hsp70 and Bag3 can suppress PCD downstream of HSF1 in cancer." (PMID 31514477, 2019). "Thus, DKK3 is a novel HSF1 target gene that regulates ECM remodelling and associated cancer cell growth and invasion; unlike other HSF1 target genes such as TGFβ or SDF1, DKK3 does not have any apparent secreted function." (PMID 30631061, 2019). "Interestingly, the activation of a cryptic Hsf1 hyper-stress program in yeast is reminiscent of the induction of non-canonical and distinct genetic programs elicited by Hsf1 in cancer cells and cancer-associated fibroblasts." (PMID 31552827, 2019). "However, mechanisms that drive HSF1 overexpression in different cancers remain largely unknown but may hold a key in understanding tumor development and the relationship to survival." (PMID 31699156, 2019). "In the future, a dual targeting of HSF-1 and Hsp90 might provide a promising approach to increase the effectiveness of radiotherapy with less side effects by reducing the concentration of hepatotoxic Hsp90 inhibitors in the treatment of cancer patients." (PMID 31569342, 2019). "Interestingly, NRF2 may engage a cross-talk with other transcription factors such as HSF1, further promoting cancer cell survival." (PMID 31121848, 2019). "Targeting HSF1-mediated signaling axes may pose an effective strategy to treat cancer." (PMID 31878360, 2019). "Whether the contribution of HSF1 to cancer progression is restricted to this specialised transcriptional profile remains to be fully understood, as competitive binding of a synthetic compound to known HSF1 targets was sufficient to reduce cell viability." (PMID 30111611, 2018).
cancer (continued). "Finally, we investigated whether CL-43-mediated HSF1 inhibition is effective in cancer cells of different origin and demonstrated that the compound elicits a similar Hsp70 level-reducing effect in cells of all seven tumor lines." (PMID 29930764, 2018). "After myriad investigations on HSF-1, the field has advanced to the phase where there is consensus that finding a potent and selective pharmacological inhibitor for this transcription factor will be a major break-through in the treatment of various human cancers." (PMID 29682483, 2018). "Several studies suggested that heat shock transcription factor (HSF)-1 translocates from the cytosol to the nucleus and regulates the expression of heat-shock proteins (HSPs) during proteotoxic stress, thereby resulting in cancer-cell survival and enhanced chemoresistance." (PMID 29423046, 2018). "Therefore, HSF1 arises as an attractive target for cancer therapy." (PMID 28257109, 2017). "Since ectopic expression of HSF1 promotes mammosphere formation and loss of HSF1 activity reduces mammosphere formation and the CD44highCD24lowESAhigh population, we asked whether combined inhibition of AKT and HSF1 could target the cancer stem cell population." (PMID 29088759, 2017). "Thus, the current understanding of HSF1 indicates it may play a role in multiple mechanisms of cancer development and maintenance and may be an attractive therapeutic target." (PMID 29088759, 2017). "How SF3B1 and HSF1 influence each other in the highly mutated landscape of a transformed cell and how the relationship between SF3B1 and HSF1 are affected in different malignancies could provide valuable clues to basic systems biology and to cancer biology." (PMID 28445500, 2017). "Additionally, our results indicate HSF1 is active in metastatic cells and cancer stem cells and may promote tumor progression to an aggressive phenotype." (PMID 29088759, 2017). "Therefore, cancer's fragile proteostatic pathway governed by HSF-1 could be a potential therapeutic target and novel biomarker by natural compounds." (PMID 29348836, 2017). "While cancer cells show decreased levels of Fbxw7 and elevated HSF1 protein levels, pathogenic polyQ-expressing cells and tissues show the opposite: increased Fbxw7 levels and increased CK2-dependent S303/307 phosphorylation of HSF1, which together drives HSF1 degradation." (PMID 28194040, 2017). "Interestingly, in cancer cells phosphorylation of S303 and S307 by distinct protein kinases is required for the interaction of HSF1 with the Fbxw7 E3 ligase, responsible for ubiquitin-dependent degradation of nuclear HSF1 in melanoma cancer cells." (PMID 28194040, 2017). "Finally HSF1 transcriptional activity can be stimulated by genetic alterations in cancer." (PMID 25954247, 2015). "This is in accordance with previous findings that a stress-inducing interference such as knockout of hsf1 in mice, which has deleterious impact on organismal survival under normal growth conditions as well as under stress, actually benefits the same organism in the case of cancer." (PMID 26192965, 2015). "Finally, the pivotal role of HSF1 in tumorigenesis is demonstrated in various animal cancer models." (PMID 25954247, 2015). "This notion was demonstrated for heat shock factor 1 (HSF1), which drives a transcriptional program different from the heat shock supporting oncogenic processes, including protein folding, stress response, cell cycle and signaling genes, to maintain highly malignant human cancers." (PMID 24576043, 2014). "In addition, HSP-independent mechanism may be involved in HSF1 regulated resistance of cancer cells to chemotherapeutics." (PMID 24165036, 2013). "The presence of HSPs could be just a secondary effect of HSF1 activity, while mechanisms of HSF1-dependent resistance of cancer cells to drugs could be connected to its interactions with other proteins and/or its impact (direct or indirect) on expression of non-HSPs genes." (PMID 24165036, 2013).
cancer (continued). "Although induction by HSF1 of the expression of molecular chaperones and other regulators of protein quality control, both folding and degradation, is well established, the precise and detailed transcriptional network that HSF1 regulates in cancer is poorly understood." (PMID 22964629, 2012). "However, some considerations must be taken when using HSF1 inhibitors because, although they seem beneficial in cancer treatment, they might, in parallel, accelerate neurodegenerative processes and aging." (PMID 24212658, 2011). "However, somatic mutations in Hsf1 have not yet been identified in human cancers, and overexpression of HSF1 does not lead to transformation, as mutant RAS does." (PMID 24212658, 2011). "Therefore, APC/C, by its effect on HSF2, could be involved in a cell cycle-dependent manner in the modulation of HSF1 activity, which could have profound effects on cancer progression." (PMID 24212658, 2011). "For it is already clear that inactivation of the heat-shock response (by knocking out both copies of the gene, HSF1, that switches on the response) greatly lowers the susceptibility of mice to induced and spontaneous cancers, without at the same time much affecting their viability and longevity." (PMID 21489209, 2011). "Therefore, HSF1 is an attractive target for cancer treatment." (PMID 20537126, 2010). "Other factors including lactate, cAMP, estrogen, ErbB2 and HSF-1 have been reported to influence LDHA expression and glycolysis in cancers, indicating that LDHA regulation is subtly controlled by a series of factors that need to be further investigated." (PMID 39930542, 2025). "By promoting cancer cell survival, metabolic reprogramming, epithelial-mesenchymal transition (EMT) process and immune evasion, HSF1 emerges as a multifaceted driver of tumorigenesis 92-94." (PMID 40520012, 2025). "Along with the current study, the link between HSF1 and MYC has been seen in cancer cells and non-cancer cells, suggesting that their interaction is physiologic but can be co-opted in cancer cells." (PMID 39831777, 2025). "Analysis of both MYC and HSF1 copy numbers indicated that MYC had amplification in 11% (1,132/9,950) of human cancers, whereas HSF1 was amplified in 8% (840/9,950) of cancers with an overlap in a substantial number of patients." (PMID 39831777, 2025). "Similar to HSF1, knocking out HSF4 delayed tumor development and cancer cell proliferation in a carcinogenesis mouse model." (PMID 40457168, 2025). "HSF1 and HSF2 are also important contributors in devastating human pathologies like cancer, neurodegenerative disorders, and neurodevelopmental disorders." (PMID 40318841, 2025). "Pharmacological HSP90 inhibition phenocopies HSP90 disappearance and thus promotes further activation and binding of HSF1 to its cognate DNA response element, thereby fully inducing the unwanted HSR in cancer cells." (PMID 40204953, 2025). "An interaction between HSF1 and MYC was also detected in OVCAR3 cells that have MYC and HSF1 wild-type (WT) genes, consistent with previous work indicating an interaction between HSF1 and MYC in non-cancer cells." (PMID 39831777, 2025). "Down-regulating HSF1 leads to decreased LDH levels and therefore ineffective glycolysis, halting growth of cancer cells." (PMID 40287736, 2025). "Among the members of the HSF family, HSF1, HSF2, and HSF4 are widely expressed in various cancers and tissues." (PMID 39248163, 2024). "Further research is needed to elucidate the mechanisms of interaction between HSF1 and ABC transporters to optimize therapeutic strategies in cancer chemoresistance." (PMID 39850800, 2024). "Targeting HSF1 in conjunction with ABC transporters, particularly ABCG2 and ABCG1, represents a promising strategy for overcoming chemoresistance in various cancers." (PMID 39850800, 2024).
cancer (continued). "In cancer cells, inhibition of MEK signaling inactivates HSF1 and induces protein destabilization, aggregation, and amyloidogenesis, which induces cell toxicity, thereby contributing to the anti-tumor effect." (PMID 39519208, 2024). "This leads to activation of the HSF1 transcription factor and the increased synthesis of its client proteins, molecular chaperones (HSP70, HSP90, HSP40, etc.), which allows cancer cells to avoid death and continue growing." (PMID 38280079, 2024). "To understand the precise mechanism by which USP7i activates HSF1, resulting in the induction of expression of HSR- and UPR-related genes, we measured the levels of the HSF1 protein in multiple types of cancer cell lines in the absence or presence of P22077." (PMID 38474017, 2024). "The results showed that Ferroptosis-related genes such as SLC3A2, HSF1, and SLC7A11 were significantly positively correlated with SPC25 in pan-cancer." (PMID 38605119, 2024). "HSF1 can also be up-regulated at the transcriptional level by NFE2L2 during oxidative stress, which is relatively higher in cancer cells." (PMID 37894333, 2023). "Phosphorylation of HSF1 at serine 326 (HSF1 pSer326) stimulates HSR and is related to the poor prognosis of cancer." (PMID 37153737, 2023). "In fact, expressions of HSF1 and DYRK2 seem to cluster together during chemotherapy response or at predicting response to cancer monotherapies." (PMID 36622366, 2023). "The current study establishes that concurrent targeting of HSF1 and DYRK2 can indeed impede cancer by inducing apoptosis faster than individual targetting." (PMID 36622366, 2023). "HSF1 pSer326 leads to HSF1 activation and the induction of HSP27 expression in cancer cells with higher expression of stem cell-related genes, negatively impacting overall survival in patients." (PMID 37153737, 2023). "Overall, multiple independent databases seem to agree that HSF1 and DYRK2 expressions overlap and correlate in diverse cancer models and also in responses to chemotherapies." (PMID 36622366, 2023). "Forty-five tissue samples from patients with HNSCC cancer were collected to determine the correlation of USP14 and HSF1 expression in the diagnosis of HNSCC, which is a novel mechanism of USP14 as a carcinogenic gene in HNSCC." (PMID 37686660, 2023). "Beyond HSR, numerous studies demonstrate that HSF1 orchestrates transcriptional programs distinct from HSR and impacts cell proliferation, survival, and metabolism related to cancer." (PMID 37958341, 2023). "High nuclear levels of DYRK2 and heat shock factor 1 (HSF1) have been detected in triple-negative breast cancer (TNBC) tissues, and high nuclear DYRK2 levels significantly reduced cancer-specific survival in TNBC and triple- and AR-negative patient samples." (PMID 37886981, 2023). "Among 16 cancer-related pathways, a high expression of USP14 was found to mainly activate the HSF1 pathway." (PMID 37686660, 2023). "Indeed, cancer cells exposed to high temperatures and to other proteotoxic stimuli (e.g., hypoxia, free radicals) activate a “heat shock response” (HS response) whose induction of HS gene expression is mainly transcriptional and is mediated by the heat shock transcription factor HSF-1." (PMID 37598177, 2023). "Previous studies have demonstrated the pivotal inhibitory effects of HSPA5, HSPB1, HSF1 and HSPH1 in cancer ferroptosis." (PMID 38041016, 2023). "As HSF-1 is a main transactivator of HSPs expression, including HSP60, HSP70, and HSP90, it has multiple effects on cancer progression, such as promoting invasion and metastasis." (PMID 37986165, 2023). "Here we describe a preferential activation in a specific subtype of cancer, BRCA-mut PDAC, and expose a new facet of HSF1’s stromal activities, affecting CAF composition." (PMID 36316305, 2022). "We have also demonstrated that there is an inverse relationship between HSF1 activity and the expression of the novel EGR4-S molecule in cancer." (PMID 35326716, 2022).